MCF2L (MCF.2 cell line derived transforming sequence like)
Description:
Guanine nucleotide exchange factor that catalyzes guanine nucleotide exchange on RHOA and CDC42, and thereby contributes to the regulation of RHOA and CDC42 signaling pathways (By similarity). Seems to lack activity with RAC1. Becomes activated and highly tumorigenic by truncation of the N-terminus (By similarity). Isoform 5 activates CDC42. [Isoform 3]: Does not catalyze guanine nucleotide exchange on CDC42.
Synonyms: KIAA0362; OST; DBS; ARHGEF14
Tractability: Antibody: UniProt places it where antibodies can reach, with high confidence; its Gene Ontology location is reachable by antibodies, with medium confidence. PROTAC: ubiquitination databases record sites on it; its protein half-life has been measured.
Gene: Protein-coding gene on chromosome 13 (112,894,378 to 113,099,742, forward strand). Ensembl gene ENSG00000126217.
Subcellular location: Cytoplasm (Isoform 5); Cell membrane; Cytoplasm (Isoform 3); Endomembrane system; Cytoplasm
Pathways (Reactome):
Signal Transduction: CDC42 GTPase cycle; G alpha (12/13) signalling events; NRAGE signals death through JNK; RAC1 GTPase cycle; RHOA GTPase cycle; RHOB GTPase cycle; RHOC GTPase cycle; RHOG GTPase cycle
Gene Ontology:
Molecular function: phosphatidylinositol binding; guanyl-nucleotide exchange factor activity
Biological process: regulation of small GTPase mediated signal transduction; intracellular signal transduction
Cellular component: cytoplasm; endomembrane system; extracellular region; plasma membrane; cytosol; membrane
Genetic constraint (gnomAD): Loss-of-function variants: 89 observed, 137.8 expected, observed/expected ratio (o/e) 0.65, 90% interval 0.54 to 0.77. The upper end of that interval is the gene's LOEUF score, 0.77, which puts it in group 3 of 6, group 1 being the genes least tolerant of losing a copy. Missense variants: 1,320 observed, 1,488.3 expected, observed/expected ratio (o/e) 0.89, 90% interval 0.85 to 0.93. Synonymous variants: 658 observed, 627.11 expected, observed/expected ratio (o/e) 1.05, 90% interval 0.98 to 1.12.
Homologues: Orthologues: macaque MCF2L (96% identical), chimpanzee MCF2L (91% identical), mouse Mcf2l (89% identical), rat Mcf2l (88% identical), guinea pig MCF2L (86% identical), pig MCF2L (84% identical), tropical clawed frog mcf2l (70% identical), dog MCF2L (69% identical), zebrafish mcf2la (63% identical), zebrafish mcf2lb (53% identical). Paralogues in human: MCF2L2 (41% identical), MCF2 (40% identical), TRIO (24% identical), KALRN (23% identical), PLEKHG4B (21% identical), PLEKHG4 (17% identical), TIAM2 (17% identical), ARHGEF40 (17% identical), TIAM1 (16% identical), PLEKHG1 (15% identical), ARHGEF7 (14% identical), PLEKHG2 (14% identical), and 10 more.
Diseases named in the same sentence as MCF2L in open-access papers:
MCF2L is named in the same sentence as 17 diseases in open-access papers, as found by Europe PMC text mining. Sharing a sentence is not in itself a finding about the gene and the disease. The quoted sentences say what the papers report.
osteoarthritis (2 papers, 2020 to 2021). A noninflammatory degenerative joint disease occurring chiefly in older persons, characterized by degeneration of the articular cartilage, hypertrophy of bone at the margins and changes in the synovial membrane. "Studies have revealed that genes such as Mcf2l, Pthrp, Col2a1, and Col9a2, associated with osteoarthritis, are dynamically expressed during zebrafish development." (PMID 32824602, 2020). "A degenerative skeletal disease such as osteoarthritis has been investigated using for example Mcf2l, Gdf5, Col9a2, col11a2 zebrafish mutants." (PMID 32824602, 2020).
atherosclerosis (1 paper, 2024). A disease characterized by the build-up of fatty material and calcium deposition in the arterial wall resulting in partial or complete occlusion of the arterial lumen. "MCF2L is a guanine-nucleotide exchange factor that participate in the Rho/Rac signaling pathways and has been reported to be involved with atherosclerosis in humans." (PMID 38181036, 2024).
breast carcinoma (1 paper, 2013). "Functionally, Mcf2l has been shown to stimulate migration of breast carcinoma cells and of Schwann cells." (PMID 23159952, 2013).
diabetic neuropathy (1 paper, 2025). A chronic, pathological complication associated with diabetes mellitus, where nerve damages are incurred due to diabetic microvascular injury involving small blood vessels that supply these nerves, resulting in peripheral and/or autonomic nerve dysfunction. "In addition, further research is needed to explore the roles of specific biomolecules implicated in diabetic neuropathy development, such as SLC30A1, TRBJ2‐7, OLFM1, TCF7L2, MCF2L, CEP295NL, CEACAM22P, TSHZ2, and PDZD4." (PMID 40692573, 2025).
infertile (1 paper, 2015). "In our previous study, random distribution and depletion of H3K9ac interaction in many loci (for example, CTSD, FLNA, MCF2L, PLXNA3, SG3GLB2, TH) of infertile men sperm have been confirmed." (PMID 25806092, 2015).
metabolic syndrome (1 paper, 2019). A cluster of metabolic risk factors for CARDIOVASCULAR DISEASES and TYPE 2 DIABETES MELLITUS. "Seven genes (WDR27, GNAS, DOK7, EDN3, MCF2L, PRKG1, and CMYA5) were selected based on genomic location and relevance to metabolic syndrome." (PMID 31170227, 2019).
cancer (3 papers, 2014 to 2021). A tumor composed of atypical neoplastic, often pleomorphic cells that invade other tissues. "Some of these genes (e.g. CENPF, MLKL, TFDP1, MCF2L) have a known influence on cancer, while others (e.g. NUP54, BBS1 and HTT) have been superficially studied under the tumoral context." (PMID 34316711, 2021).
tumor (2 papers, 2021 to 2025). "First, gene-level differential analysis of the stromal component of KIRC against the other eight tumor types revealed 941 differentially expressed (DE) genes (q< 0.05, BH adjusted), including the Mcf2l, Exoc3l2, Olfr558, and Chrm2 listed as the top-ranked genes." (PMID 35079698, 2021). "This suggests that MCF2L might function as a tumor suppressor gene in this context." (PMID 39843641, 2025).
hematological malignancies (1 paper, 2011). "ACACA, RARA, NOTCH1 and NUP214 are known to form translocations in various types of hematological malignancies while many other fusion genes involve suspected oncogenes, such as RPS6KB1 (RPS6KB1-TMEM49 and RPS6KB1-SNF8), GSDMB (TATDN1-GSDMB) and MCF2L (LAMP1-MCF2L)." (PMID 21247443, 2011).
MCF2L also shares sentences with these, for which no sentence is quoted: angina (1 paper); colonic carcinoma (1); diabetes (1); ischemic heart disease (1); leiomyoma (1); leiomyosarcoma (1); myocardial infarction (1); Stroke (1).